NUF2 (NUF2 component of NDC80 kinetochore complex)
Diseases named in the same sentence as NUF2 in open-access papers (continued):
Sharing a sentence is not in itself a finding about the gene and the disease.
cancer (61 papers, 2013 to 2025). A tumor composed of atypical neoplastic, often pleomorphic cells that invade other tissues. "NUF2, a protein within the NDC80 complex, has been identified as a cancer gene candidate because missense mutations, found across different tumor samples, cluster within NUF2’s calponin homology domain." (PMID 40161439, 2025). "In this study, we examined a NUF2 cancer-associated mutation in a simple and well-studied organism,Saccharomyces cerevisiae, to elucidate its effects on cell division." (PMID 40161439, 2025). "The aim of this study was to elucidate the effects that the human cancer associated missense mutations in NUF2 have on kinetochore composition and function by examining them inS. cerevisiae." (PMID 40161439, 2025). "A study found that missense mutation in the NUF2 gene was linked to cancer development and hence, its inhibition resulted in the suppression of tumor growth leading to cancer cells apoptosis." (PMID 36900109, 2023). "Aberrant expression of the gene encoding the Ndc80 kinetochore complex component (NUF2) reportedly contributes to the progression of several human cancers." (PMID 35814368, 2022). "Evidence has shown that NUF2 is overexpressed in a series of human cancers and is significantly associated with poor prognosis." (PMID 36620547, 2022). "The genes assayed were neuroendocrine-associated genes (INSM1, ASCL1, NRCAM, and SNAP25), one gene centered in the gene regulatory network (NUF2), and five possibly cancer-associated genes (PTP4A3, RFC4, REST, APEH, and FBLN2)." (PMID 34395507, 2021). "The CH domain of NUF2 is conserved acrossH. sapiens andS. cerevisiae, so we performed a structural alignment of both proteins to identify the location of the cancer-associated residues in the yeast protein." (PMID 40161439, 2025). "We speculated that the NUF2 cancer associated missense mutations could affect the structure of the CH domain and alter its protein function within cancerous cells." (PMID 40161439, 2025). "Analysis of mutations in the PanCancer compendium data set of 4,742 tumours from 21 cancer types revealed mis-sense mutations in NUF2 that could affect chromosome segregation and result in aneuploidy." (PMID 30364636, 2018). "Previous studies have reported that NUF2 is associated with several human cancers." (PMID 29190974, 2017). "Inhibition of NUF2 expression was reported to suppress the growth of cancer cells and induce apoptosis." (PMID 38472943, 2024). "NUF2 exhibits a Cancer germline-like expression profile in GTEx with predominant expression in testis and marginal expression in most other tissues." (PMID 39835134, 2024). "Deletion of NUF2 can significantly inhibit the tumorigenesis and progression of cancers in vitro and in vivo." (PMID 39242581, 2024). "This study investigated the relationship between NUF2 expression in the cancer tissues of patients with NSCLC who underwent curative-intent resection and their clinicopathological factors and prognosis." (PMID 38472943, 2024). "The data demonstrate that PLK1 and NUF2 are the most essential genes among these cancers, with the lowest Chronos scores." (PMID 39392349, 2024). "NUF2 was upregulated in various kinds of cancers and regarded as a promising antitumor therapeutic target and prognostic factor." (PMID 39242581, 2024). "Nuf2 has been reported as a prognostic marker and therapeutic target in several types of cancer since it becomes elevated following the onset of cancer and promotes tumorigenesis." (PMID 38994368, 2024). "We performed quantitative RT-PCR analysis of NUF2 gene expression in cancer and corresponding normal lung tissues isolated from 88 patients with NSCLC." (PMID 38472943, 2024). "NUF2 is a critical cell cycle regulator and has been reported to be a prognostic factor for several cancers." (PMID 38472943, 2024).
cancer (continued). "This retrospective study quantified NUF2 expression in the cancer tissues of 88 patients with NSCLC who underwent complete resection using real-time polymerase chain reaction and investigated its relationship with clinicopathological features and prognosis." (PMID 38472943, 2024). "Through the online website TIMER, we evaluated the transcription profile of NUF2 across a variety of different cancer types and found that NUF2 mRNA was highly expressed in BRCA patients." (PMID 36835637, 2023). "NUF2 has been identified as a prognostic factor in various human cancers, regulating cell apoptosis and proliferation." (PMID 36835637, 2023). "Evidences were obtained regarding the roles of NUF2 in the progression of different kinds of cancers." (PMID 36670423, 2023). "Accumulating evidence indicates that NUF2 plays a very important role in the progression of kinds of malignant tumors." (PMID 36670423, 2023). "Although NUF2 (Ndc80 kinetochore complex component) has been suggested to play an important role in the development of many cancers, but little is known about its function and the roles of proteins that regulate NUF2 in OC." (PMID 36670423, 2023). "NUF2 has been previously reported to play an essential role in tumorigenesis and is upregulated in a variety of human cancers." (PMID 37138262, 2023). "There are mounting evidences that NUF2, as an oncogene, is closely related to the growth, apoptosis, invasion and metastasis of various tumor cells and poor prognosis of cancer patients." (PMID 36670423, 2023). "The pan-cancer analysis of NUF2 in TCGA database showed that NUF2 was highly expressed in most tumors, including in CCA." (PMID 37056930, 2023). "The Ndc80 kinetochore complex component (NUF2) is involved in the development and progression of several cancers." (PMID 35813477, 2022). "In this study, we evaluated the expression of NUF2 in LUAD as described in the following five cohorts: The Cancer Genome Atlas (TCGA), Genotype-Tissue Expression (GTEx), Gene Expression Omnibus (GEO), ONCOMINE, and UALCAN." (PMID 35814368, 2022). "Previous studies have indicated that NUF2 functions as an oncogene in different types of malignant tumors." (PMID 36620547, 2022). "Pan-cancer analysis in 31 distinct tumor types has revealed the overexpression of NUF2 in 23 cancer types." (PMID 36499051, 2022). "NDC80 kinetochore complex component (NUF2) is upregulated and plays an important role in various human cancers." (PMID 36620547, 2022). "Studies have found that IGF2BP3 can stabilize CDKN2B-AS1 through epigenetic activation of NUF2 transcription to drive the progression of KIRC malignant tumors." (PMID 36098680, 2022). "The association between NUF2 and immunosuppressive gene levels implies that NUF2 has a major function in regulation of cancer immunology." (PMID 35600043, 2022). "NUF2 is found to be a prognostic biomarker and therapeutic target which is correlated with the immune infiltration in patients with cancer." (PMID 35873497, 2022). "Together, these results highlight a specific role of NUF2 in tumor growth and progression, making it a potential and effective candidate for molecule-targeted therapy in many cancers." (PMID 35813477, 2022). "Nuf2 promotes the tumorigenesis and tumor development and is highly expressed in various human cancers, including serous adenocarcinoma, renal cell carcinoma, cholangiocarcinoma, and colorectal, lung, ovarian, gastric, and bladder cancers." (PMID 33767990, 2021). "Although the high expression of NUF2 has been reported in many different types of human cancers, the multi-omics analysis in non-small cell lung cancer (NSCLC) of NUF2 remains to be elucidated." (PMID 34178642, 2021). "We found 82 and 2178 gained and lost edges shared across 9 cancer types, respectively, with the Q9BZD4 (NUF2) and P04629 (NTRK1) proteins associated with the largest number of perturbations." (PMID 32152446, 2020).
cancer (continued). "Of note, 6 CTA genes CEP55, KIF2C, TTK, OIP5, CASC5, and NUF2 had higher expression levels in the higher-TMB subtype of at least 15 cancer types, while had higher expression levels in the lower-TMB subtype of at most 3 cancer types." (PMID 30634925, 2019). "As well as results from TCGA data, NUF2 overexpression has been reported in a diverse set of cancers including pancreatic, gastric and colorectal, lung (both small cell and non-small cell), cholangiocellular, urinary bladder and renal." (PMID 30364636, 2018). "The functional importance of NUF2 in cancer is suggested through screen based studies; an RNAi lethality screen in the Epithelial Ovarian Cancer (EOC) cell line A1847 and other EOC lines identified the factor as important for preventing apoptosis." (PMID 30364636, 2018). "Silencing of NUF2 significantly inhibited the proliferation of cancer cells in vitro, through inducing cell cycle arrest at the G0/G1 phase." (PMID 29190974, 2017). "Notably, overexpression of genes involved in the mitotic spindle checkpoint, such as NUF2, MAD2L1, and BUB1, has been linked to chemotherapeutic responses in various cancer types." (PMID 40643514, 2025). "In addition, NUF2 has been found to drive cancer development through inhibiting autophagic degradation of oncogene TFR1 or affecting the transcription of HMGA2." (PMID 39242581, 2024). "For the first time, our study leveraged high-throughput sequencing data from public databases and the WGCNA method to obtain modules in PCa that are closely related to stem cell characteristics and explored the biological role of the cancer stem cell characterization-related gene NUF2 in PCa." (PMID 39703688, 2024). "KIF14, NUF2, and ESPL1, have been associated with poorer prognosis in various cancers." (PMID 39766071, 2024). "For example, NUF2 was identified as a new cancer stem cell indicator." (PMID 39242581, 2024). "Growing evidence suggests that NUF2 plays a critical role in the tumorigenesis of human cancers." (PMID 37138262, 2023). "NUF2 mRNA expression profiles of pan-cancer patients were downloaded from the online tool TIMER." (PMID 36835637, 2023). "It has been reported that NUF2 expression is significantly upregulated in many other cancers." (PMID 37138262, 2023). "All sets of figures showed high expression of NUF2 in ccRCC, indicating that NUF2 may play an irreplaceable role in tumor growth and development of various cancers, especially ccRCC, and may be a meaningful gene in ccRCC and other cancers." (PMID 37138262, 2023). "The differential effect of NUF2 on the cycle may indicate that the NUF2 gene has various effects on epigenetic regulation in different cancer types." (PMID 35814368, 2022). "Cancer patients need careful observation after treatment, and Nuf2 may be used, to some extent, as a prognostic marker to reduce the risk of recurrence." (PMID 33767990, 2021). "Similarly, Nuf2 has been proved to be highly expressed in many other cancer types, indicating its wide applicability and functional conservation." (PMID 33767990, 2021). "Shared genes by all cancers with an adverse prognosis (high positive global meta-z-scores), such as MAD2L1, CCNB1, NUF2 and UBE2C, were associated with gene ontology (GO) enrichment analysis terms related to proliferation, replication and mitosis, similar to adult tumors." (PMID 33670534, 2021). "GO enrichment analysis shows that NUF2 is mainly involved in cell division, mitotic nuclear division, chromosome segregation and sister chromatid cohesion, their dysregulation impact significantly on development of cancer." (PMID 33005492, 2020). "Although the agents targeting the components of kinetochore complex including Ndc80 and Nuf2 have been shown to have anti-cancer effects, this is the first report, to the best of our knowledge, to show the mechanism to suppress cancer cell proliferation through the degradation of Mis12." (PMID 31222108, 2019).
cancer (continued). "Study suggests NUF2 as a novel prognostic biomarker and therapeutic target for cancers." (PMID 31788359, 2019). "Furthermore, NUF2 has been reported to play a role in tumorigenesis of various types of human cancers." (PMID 29190974, 2017). "Moreover, LCM of malignant hepatocytes also revealed up-regulation of unique genes associated with cancer and signaling pathways, including two novel HCC-associated cancer testis antigen genes, NUF2 and TTK." (PMID 25141867, 2014). "NUF2 may play a critical role in developing PCa by affecting cancer stemness." (PMID 39703688, 2024). "Thus, NUF2 is recognized as a type of cancer–testis antigen." (PMID 38472943, 2024). "Recent research also revealed that NUF2 may drive cancer progression through other mechanisms." (PMID 39242581, 2024). "The Kaplan-Meier curve and log-rank test analysis revealed that increased NDC80, NUF2, SPC24, and SPC25 mRNA levels were all significantly associated with the overall survival (OS), disease-free survival (DFS), disease-free interval (DFI), and progression-free interval (PFI) of pan-cancer samples." (PMID 39513104, 2024). "NUF2 component of NDC80 kinetochore complex (NUF2) is a component of a conserved protein complex associated with the centromere, and one study had demonstrated that NUF2 upregulation is a common feature of many cancers (TCGA-SARC dataset was also incorporated in this study)." (PMID 35126643, 2022). "Previous reports have suggested that Nuf2 may play a role in various human cancers." (PMID 33767990, 2021). "GEPIA, The Cancer Genome Atlas (TCGA) database, GSEA and western blot were used to detect the potential signaling pathways related to the roles of HNRNPA2B1 and NUF2 in OC cells." (PMID 36670423, 2023). "The subgroup analysis results showed that the promotor methylation of NUF2 was possibly impact by stage, smoking status and N stage of AJCC TMN cancer stage." (PMID 34178642, 2021). "Among these genes, Nuf2 had the strongest positive correlation with CENPL in HCC and many other common cancers." (PMID 34607313, 2021). "Markedly, the CTA genes ATAD2, CEP55, FANCA, KIF2C, NUF2, OIP5, and PBK had significantly positive expression correlations with the PLK1 expression in 30 cancer types (Pearson correlation, FDR<0.1)." (PMID 30631355, 2018). "Among them, seven genes of CDCAs (CDCA1/NUF2: P = 2.73E-22, CDCA2: P = 1.52E-16, CDCA3: p = 1.50E-20, CDCA5: P = 1.77E-20, CDCA6/CBX2: P = 6.87E-19, CDCA7: P = 5.92E-16, and CDCA8: P = 1.67E-18) were all up-regulated in 19 cancer datasets." (PMID 33665158, 2020). "The cancer patients with higher expression of NDC80, NUF2, SPC24, and SPC25 were predicted to have worse OS, DFS, DFI, and PFI, which suggested that NDC80 complex components may be potential prognostic indicator molecules in pan-cancer." (PMID 39513104, 2024). "Thus, increased NUF2 in EOC and other cancers may directly or indirectly regulate the PI3K-Akt and MAPK signaling because of NUF2 link with microtubules." (PMID 36620547, 2022). "Interestingly, NUF2 expression was positively correlated with Th1 and Th2 cells but negatively correlated with DC cells and NK cells, suggesting that NUF2 may play two roles in tumor immune infiltration, a finding that was first reported in BRCA but has since been reported in other cancers." (PMID 36835637, 2023). "Moreover, at the multi-cancer level, known cancer drivers such as CDC45 and NUF2 were identified to be involved in edgetic gains while NTRK1, PRPH and MYOC were determined to be involved in edgetic losses and may serve as targets for widely applicable therapeutic interventions." (PMID 32152446, 2020).
tumor (59 papers, 2011 to 2025). "Our results showed that mRNA and protein abundance of NUF2 was higher in PCa tumor tissues, and a high NUF2 expression level was associated with poorer DFS in PCa patients." (PMID 39703688, 2024). "It reveals the potential regulating role of NUF2 in polarization of tumor-associated macrophages (TAM) and DCs." (PMID 34178642, 2021). "Our results revealed that low expression in ESCC is associated with worse outcomes, and NUF2 can efficiently distinguish tumor tissues from normal tissue (AUC= 99.2%), suggesting its diagnostic value for ESCC." (PMID 33403046, 2021). "Correlation analysis also showed that NUF2 was mainly positively associated with cell cycle and tumor-related genes." (PMID 34178642, 2021). "The association between Nuf2 expression and tumor-infiltrating immune cell status was investigated based on immune biomarker gene expression levels in HCC." (PMID 33767990, 2021). "Regarding PAAD, increased CDCA expression along with advanced PAAD tumor stage, NUF2, CDCA2, CDCA3, CDCA4 and CDCA5 expression are risk factors for poor prognosis, while CBX2 expression is a protective factor (P < 0.05)." (PMID 33437202, 2021). "Nuf2 can be cleaved into alternative splice variants and expressed differentially between tumor tissues and the corresponding normal tissues." (PMID 33767990, 2021). "Down-regulation of Nuf2 expression can inhibit the proliferation of tumor cells, while over expression of Nuf2 is associated with poor prognosis." (PMID 33767990, 2021). "NUF2 was previously reported to be closely linked to the tumor microenvironment." (PMID 37138262, 2023). "Furthermore, the TCGA dataset revealed that elevated NUF2 expression was associated with large tumor size, higher histologic grades, advanced tumor node metastasis (TNM) stages, and metastases." (PMID 35813477, 2022). "Our findings elucidated that NUF2 may play an important role in cell cycle, and significantly associated with tumor-related gene in NSCLC; we consider that NUF2 may be a prognostic biomarkers in NSCLC." (PMID 34178642, 2021). "In addition, NUF2 was positively linked to tumor immune cells in ccRCC." (PMID 37138262, 2023). "Similarly, a reduction in NUF2 inhibited tumor growth caused by apoptosis in human tumor cells." (PMID 32565735, 2020). "A previous study mapped somatic missense mutations, identified from different cancerous tumor samples, onto the available PDB (2VE7) structure of NUF2 and found that they significantly cluster within its CH domain." (PMID 40161439, 2025). "Several studies have indicated that NUF2 is upregulated in tumor tissues and regarded as a pro-tumor factor." (PMID 40220284, 2025). "The IHC staining of mice tumor tissues confirmed that NUF2 knockdown decreased the expression of proliferative nuclear marker Ki67." (PMID 39242581, 2024). "To investigate the effect of NUF2 on tumor growth in vivo, we implanted control or NUF2-knockdown ATC cells into zebrafish and nude mice." (PMID 39242581, 2024). "In general, these results showed that the upregulation of magnesium transporters was partly responsible for NUF2-mediated tumor progression in ATC." (PMID 39242581, 2024). "Consistent with its function, NUF2 was widely considered to play a pro-tumor role by regulating cell division and DNA replication." (PMID 39242581, 2024). "The results indicated that NUF2 was primarily expressed in the cytoplasm of PCa cells and that the protein expression level of NUF2 in tumor tissues was significantly higher than in normal prostate tissues." (PMID 39703688, 2024). "Firstly, we detected NUF2 expression in PCa tumor tissues and their corresponding adjacent normal tissues by IHC analysis." (PMID 39703688, 2024). "Our finding showed that NUF2 was required for the survival and tumor growth of ATC, which was dependent on NUF2-mediated magnesium ion homeostasis." (PMID 39242581, 2024).